RHOF (ras homolog family member F, filopodia associated)
Description:
Plasma membrane-associated small GTPase which cycles between an active GTP-bound and an inactive GDP-bound state. Causes the formation of thin, actin-rich surface projections called filopodia. Functions cooperatively with CDC42 and Rac to generate additional structures, increasing the diversity of actin-based morphology.
Synonyms: ARHF; RIF; FLJ20247
Tractability: Antibody: UniProt places it where antibodies can reach, with high confidence; its Gene Ontology location is reachable by antibodies, with high confidence. PROTAC: ubiquitination databases record sites on it; its protein half-life has been measured.
Gene: Protein-coding gene on chromosome 12 (121,777,754 to 121,803,403, reverse strand). Ensembl gene ENSG00000139725.
Subcellular location: Cell membrane; Cytoplasm, cytoskeleton
Subcellular location (Human Protein Atlas): Golgi apparatus; Nucleoplasm
Pathways (Reactome):
Immune System: Neutrophil degranulation
Signal Transduction: RHOF GTPase cycle
Gene Ontology:
Molecular function: GTPase activity; guanyl-nucleotide exchange factor activity; protein kinase binding; G protein activity; GTP binding
Biological process: actin filament organization; cell migration; regulation of actin cytoskeleton organization; regulation of small GTPase mediated signal transduction; small GTPase-mediated signal transduction
Cellular component: extracellular exosome; cytoskeleton; cytosol; plasma membrane; secretory granule membrane
Genetic constraint (gnomAD): Loss-of-function variants: 25 observed, 22.86 expected, observed/expected ratio (o/e) 1.09, 90% interval 0.8 to 1.53. The upper end of that interval is the gene's LOEUF score, 1.53, which puts it in group 6 of 6, group 1 being the genes least tolerant of losing a copy. Missense variants: 285 observed, 273.94 expected, observed/expected ratio (o/e) 1.04, 90% interval 0.94 to 1.15. Synonymous variants: 135 observed, 124.75 expected, observed/expected ratio (o/e) 1.08, 90% interval 0.94 to 1.25.
Homologues: Orthologues: chimpanzee RHOF (99% identical), macaque RHOF (98% identical), rat Rhof (92% identical), mouse Rhof (91% identical), guinea pig RHOF (91% identical), dog RHOF (74% identical), tropical clawed frog rhof (66% identical), pig RHOF (65% identical), zebrafish rhof (62% identical), rabbit RHOF (51% identical). Paralogues in human: RHOD (49% identical), RAC2 (47% identical), RHOA (46% identical), RAC1 (45% identical), RAC3 (45% identical), RHOC (45% identical), RHOB (44% identical), RHOG (43% identical), RHOJ (43% identical), RHOQ (43% identical), CDC42 (40% identical), RND3 (38% identical), and 10 more.
Diseases named in the same sentence as RHOF in open-access papers:
RHOF is named in the same sentence as 21 diseases in open-access papers, as found by Europe PMC text mining. Sharing a sentence is not in itself a finding about the gene and the disease. The quoted sentences say what the papers report.
hepatocellular carcinoma (3 papers, 2021 to 2022). A malignant tumor that arises from hepatocytes. "Furthermore, RHOF was shown to be frequently up-regulated in hepatocellular carcinoma, and increased RHOF expression is associated with poor clinical outcome." (PMID 35454871, 2022). "RHOF also acts as a protector of hepatocellular carcinoma and promotes metabolic reprogramming under glucose deprivation conditions." (PMID 34953498, 2021). "The RHOF expression was associated with tumor-lymph node-metastasis stage, T grade, metastatic status, recurrence, and survival of hepatocellular carcinoma, and RHOF plays a key role in promoting HCC cell migration, invasion and EMT by regulating Warburg effect." (PMID 36454866, 2022).
lymphoma (3 papers, 2016 to 2021). A malignant (clonal) proliferation of B- lymphocytes or T- lymphocytes which involves the lymph nodes, bone marrow and/or extranodal sites. "RhoF was highly expressed in hematological malignancies including lymphoma and AML, whereas RhoD was expressed at a low level in leukemia." (PMID 34405015, 2021). "Moreover, relatively elevated levels of RHOF were observed in lymphomas derived from the germinal centre." (PMID 26860319, 2016).
acute myeloid leukemia (2 papers, 2021 to 2023). Acute myeloid leukemia (AML) is a group of neoplasms arising from precursor cells committed to the myeloid cell-line differentiation. "Next, to determine the mRNA expression features of RhoF and RhoD in non-M3 AML patients, the RhoF and RhoD expression levels in TCGA datasets (Acute Myeloid Leukemia, NEJM 2013, n=157) 24 were compared, revealing a high RhoF expression level over that of RhoD." (PMID 34405015, 2021).
glioma (2 papers, 2015 to 2022). A benign or malignant brain and spinal cord tumor that arises from glial cells (astrocytes, oligodendrocytes, ependymal cells). "Seven Rho GTPases (RND1, RND3, RAC3, RHOA, RAC2, RAC1 and RHOC) showed a significantly greater connectivity in grade IV glioma and seven (CHP, RHOD, RHOF, RHOB, RHOQ, RND2, RHOBTB3) showed greater connectivity in grade II glioma." (PMID 26132659, 2015).
lymph node metastasis (2 papers, 2017 to 2022). "We identified associations between miR-3656 and TNM stage, lymph node metastasis and tumor location, whereas for RHOF, expression was associated with TNM stage, lymph node metastasis and T classification." (PMID 29048402, 2017). "However, our study found for the first time that methylation of RHOF, CRMP1, BNIP3 and HOXA5 promoters is associated with lymph node metastasis." (PMID 36454866, 2022). "However, methylation of RHOF, CRMP1, BNIP3 and HOXA5 promoters has not been reported to be associated with lymph node metastasis, and our study is the first to find that methylation of these gene promoters is associated with lymph node metastasis." (PMID 36454866, 2022).
pancreatic cancer (2 papers, 2023 to 2025). "For prognostic prediction, we developed an immune-related prognostic risk model (IRPM) based on four immune-related prognostic genes in pancreatic cancer, RHOF, CEP250, TSC1, and KIF20B." (PMID 38203311, 2023). "Previous studies have shown that CD8+T cells are major drivers of anti-tumor immunity, which suggests that RHOF expression is related to pancreatic cancer and the immune microenvironment." (PMID 38203311, 2023). "Moreover, a recent study showed that overexpression of the small GTPase RHOF in pancreatic cancer cells upregulated c-Myc, which in turn enhanced PKM2 transcription, augmented glycolysis, and increased lactate production." (PMID 41458606, 2025). "Moreover, the utilization of the EdU assay confirmed a noticeable deceleration in the growth of pancreatic cancer cells due to decreased RHOF expression." (PMID 38203311, 2023). "In light of the accuracy of the IRPM score in the prognostic assessment of PC patients and the significance of the RHOF gene in prognostic models, we conducted a series of in vitro experiments to investigate its role in the occurrence and progression of pancreatic cancer." (PMID 38203311, 2023).
breast carcinoma (1 paper, 2022). "Our study found hypomethylation of the RHOF promoter in lymph node metastatic breast cancer tissue, which is likely to lead to elevated RHOF expression in positive lymph node tissue compared to negative lymph node tissue." (PMID 36454866, 2022). "But TCGA data showed that RASGRF2, AKR1B1 and CRMP1 were low expressed in breast Cancer tissues, while RHOF was high expressed in breast Cancer tissues." (PMID 36454866, 2022). "Therefore, methylation of RHOF promoter has potential as a therapeutic target and prognostic biomarker for breast cancer with ALNM." (PMID 36454866, 2022). "In addition, Cancer Genome Atlas (TCGA) data showed that RASGRF2, AKR1B1 and CRMP1 were low expressed in breast Cancer tissues, while RHOF was high expressed in breast Cancer tissues." (PMID 36454866, 2022). "However, elevated RHOF expression is likely to lead to ALNM of breast cancer." (PMID 36454866, 2022). "The results showed that compared with negative lymph node breast cancer tissues, RHOF promoter methylation levels were decreased in positive lymph node breast cancer tissues, while AKR1B1, RASGRF2, and CRMP1 gene promoter methylation levels were increased." (PMID 36454866, 2022). "Therefore, our study identified RHOF, CRMP1, BNIP3 and HOXA5 as novel candidate methylation biomarkers, which can be used to predict ALNM in breast cancer or ER-positive and HER2-negative breast cancer." (PMID 36454866, 2022).
eosinophilic esophagitis (1 paper, 2019). Eosinophilic esophagitis (EoE) is a chronic, allergic disease of the esophagus characterized clinically by symptoms of esophageal dysfunction (including vomiting, dysphagia, feeding disorders, food impaction and abdominal pain) which persist after treatment with proton pump inhibitors (PPIs). "Finally, we find that RHOF is upregulated in eosinophilic esophagitis, an important esophageal inflammatory disease in humans." (PMID 30998758, 2019). "To determine whether RHOF might have a role in human esophageal inflammation, we examined the expression of RHOF in an in vitro model of the human inflammatory disease eosinophilic esophagitis (EoE) and in human EoE samples." (PMID 30998758, 2019).
esophageal squamous cell carcinoma (1 paper, 2019). Esophageal squamous cell carcinoma (ESCC) is a type of esophageal carcinoma (EC) that can affect any part of the esophagus, but is usually located in the upper or middle third. "Based on these findings, we propose a model in which KLF4 acts via RHOF to induce NFκB signaling, leading to esophageal epithelial inflammation and esophageal squamous cell cancer." (PMID 30998758, 2019).
liver cancer (1 paper, 2022). An epithelial or non-epithelial malignant neoplasm that arises from the liver. "RHOF plays a critical role in the regulation of liver cancer metastasis." (PMID 36589226, 2022).
myopia (1 paper, 2019). "We found over 3-fold hypermethylation of promoters of two Rho family genes, RHOD and RHOF, to be significantly associated with myopia." (PMID 30858441, 2019).
cancer (8 papers, 2016 to 2023). A tumor composed of atypical neoplastic, often pleomorphic cells that invade other tissues. "Furthermore, we found a positive correlation between RHOF expression and the activity of several steps in the cancer immune cycle." (PMID 38203311, 2023). "Again, no cancer-related point mutations have been reported for RHOD or RHOF, although they have both been shown to be differently expressed (mostly overexpressed) in cancer." (PMID 35454871, 2022). "The exact mechanism for this cancer development is still not well understood, but it might be due to the ability of RhoH to regulate the activities of other cancer-related small Rho GTPases, including RhoA, Cdc42, Rac1 and RhoF." (PMID 33923951, 2021). "The involvement of RHOF in cancer development has been reported, but whether it is also implicated in regulating EMT has never been investigated." (PMID 29048402, 2017). "Among these, RAC1 and RHOA are already present in the Cancer Gene Census, adding confidence to the hypothesis that also RHOF might play a role in cancer." (PMID 26860319, 2016). "The signaling landscape that accompanies Ephexin3 in various cancer types included the tyrosine kinase receptor MET and the tyrosine phosphatase receptor PTPRF, the serine/threonine kinases MARK2 and PAK6, the Rho GTPases RHOD, RHOF and RAC1, and the cytoskeletal regulator DIAHP1." (PMID 38003617, 2023). "To further clarify the possible role of RHOF in the tumor microenvironment, we analyzed single-cell sequencing data through the TISCH database (a scRNA-seq database that provides extensive cell type annotations at the single-cell level, allowing for TME exploration across various cancers)." (PMID 38203311, 2023).
tumor (7 papers, 2017 to 2025). "Therefore, we can boldly speculate that tumor suppressor genes antagonize the tumor-promoting effect of RhoF." (PMID 34405015, 2021). "Integrated analysis of GTEx (normal, n = 171) and TCGA (tumor, n = 179) datasets revealed higher expression of CHST11, SLC16A1, RHOF, MAN1C1, SPRR1B, and ANO6 in tumors." (PMID 41346619, 2025). "In this study, 105 immune-related genes from tumor gene sets were identified as IRPGs in PAAD patients by the univariate Cox analysis, and 4 genes of IRPGs, RHOF, CEP250, TSC1, and KIF20B were then used to construct the IRPM." (PMID 38203311, 2023). "More importantly, the crucial gene in the prognostic model, RHOF, a member of the Rho GTP enzyme family, has been extensively studied for its role in regulating tumor cell adhesion, migration, epithelial-mesenchymal transition, and drug resistance." (PMID 38203311, 2023).
inflammation (1 paper, 2019). Aberrant reaction of the microcirculation characterized by movement of fluid and leukocytes from the blood into extravascular tissues. "Finally, RHOF was upregulated in a model of esophageal inflammation, in which PBMCs stimulated with interleukins are co-cultured with esophageal epithelial cells in organotypic culture." (PMID 30998758, 2019).
RHOF also shares sentences with these, for which no sentence is quoted: developmental delays (2 papers); Autoimmunity (1); leukemia (1); microcephaly (1); myeloid leukemia (1); neurodevelopmental disorder (1); Obesity (1).